TMEM138 (transmembrane protein 138)
Description:
Required for ciliogenesis.
Synonyms: HSPC196; JBTS16
Tractability: Antibody: UniProt predicts a signal peptide or a membrane-spanning region. PROTAC: ubiquitination databases record sites on it.
Gene: Protein-coding gene on chromosome 11 (61,361,964 to 61,377,890, forward strand). Ensembl gene ENSG00000149483.
Subcellular location: Vacuole membrane; Cell projection, cilium
Subcellular location (Human Protein Atlas): Microtubules; Primary cilium
Gene Ontology:
Biological process: cilium assembly
Cellular component: cilium; vacuolar membrane
Genetic constraint (gnomAD): Loss-of-function variants: 5 observed, 11.34 expected, observed/expected ratio (o/e) 0.44, 90% interval 0.23 to 0.93. The upper end of that interval is the gene's LOEUF score, 0.93, which puts it in group 3 of 6, group 1 being the genes least tolerant of losing a copy. Missense variants: 151 observed, 162.57 expected, observed/expected ratio (o/e) 0.93, 90% interval 0.81 to 1.06. Synonymous variants: 70 observed, 68.13 expected, observed/expected ratio (o/e) 1.03, 90% interval 0.85 to 1.25.
Gene-disease validity (ClinGen):
ClinGen rates the evidence that TMEM138 causes each of these diseases.
ciliopathy (autosomal recessive): Moderate. A genetic disorder of the cellular cilia or the cilia anchoring structures, the basal bodies, or of ciliary function.
Homologues: Orthologues: chimpanzee TMEM138 (99% identical), dog TMEM138 (94% identical), pig TMEM138 (94% identical), guinea pig TMEM138 (85% identical), macaque TMEM138 (79% identical), mouse Tmem138 (77% identical), zebrafish tmem138 (68% identical), Caenorhabditis elegans tmem-138 (31% identical), Drosophila melanogaster CG13999 (30% identical).
Diseases named in the same sentence as TMEM138 in open-access papers:
TMEM138 is named in the same sentence as 17 diseases in open-access papers, as found by Europe PMC text mining. Sharing a sentence is not in itself a finding about the gene and the disease. The quoted sentences say what the papers report.
Joubert syndrome (3 papers, 2020 to 2025). Joubert syndrome (JS) is characterized by congenital malformation of the brainstem and agenesis or hypoplasia of the cerebellar vermis leading to an abnormal respiratory pattern, nystagmus, hypotonia, ataxia, and delay in achieving motor milestones. "TMEM138 is a connecting protein for cilium transport and biogenesis, and mice with mutated TMEM138 suffer from impaired primary cilia, learning and memory, resulting in Joubert syndrome." (PMID 36922987, 2023). "The mutations of TMEM138 are reported to be responsible for Joubert syndrome, which is inconsistent with the phenotype of our family." (PMID 33218330, 2020). "TMEM138, a transmembrane protein, was initially linked to Joubert syndrome (JS)." (PMID 40432436, 2025). "Mutations in TMEM138 can result in severe neurodevelopmental disorders like Joubert syndrome." (PMID 40432436, 2025).
ciliopathy (2 papers, 2019 to 2021). "Four different homozygous single nucleotide variants (SNVs) were detected in 4 known ciliopathy genes (TMEM231,TMEM138,WDR19 andBBS9) and were confirmed by Sanger sequencing." (PMID 34354814, 2021). "In addition to this, 661W cells express several syndromic ciliopathy disease genes which are not expressed at all in hTERT-RPE1 cells, including B9d1, B9d2, Evc2, Pkd1, and Tmem138." (PMID 31024622, 2019).
Azoospermia (1 paper, 2025). Absence of any measurable level of sperm,whereby spermatozoa cannot be observed even after centrifugation of the semen pellet. "Mutations in TMEM138 have been linked to azoospermia and infertility, highlighting the need for a deeper understanding of its mechanisms for potential diagnostic and therapeutic advancements in reproductive system diseases." (PMID 40432436, 2025).
epilepsy (1 paper, 2025). A brain disorder characterized by episodes of abnormally increased neuronal discharge resulting in transient episodes of sensory or motor neurological dysfunction, or psychic dysfunction. "Furthermore, TMEM138 is implicated in various other conditions such as nervous system malformations, epilepsy, oral-facial-digital syndrome, and tumors." (PMID 40432436, 2025).
lung carcinoma (1 paper, 2025). "TMEM138 has been identified as a potential tumor suppressor gene for lung cancer, with links to Notch, Hippo, MAPK, and other signaling pathways related to cell proliferation, differentiation, and apoptosis." (PMID 40432436, 2025). "Additionally, Zhao and colleagues employed CRISPR/Cas9 knockout library technology to conduct a whole-genome screening, identifying 38 potential tumor suppressor genes for lung cancer, with TMEM138 being one of them." (PMID 40432436, 2025).
oral-facial-digital syndrome (1 paper, 2025). "Additionally, mutations in TMEM138 and other genes have been associated with Meckel-Gruber syndrome and type VI oral-facial-digital syndrome." (PMID 40432436, 2025).
retinal detachment (1 paper, 2024). An eye emergency condition which may lead to blindness if left untreated. "A similar widespread IS Rho mislocalization was also seen in a RPGR mutant dog model of X-linked RP, in a knockout mouse for the CC-localized and JBTS-associated Tmem138 membrane protein, and after experimental retinal detachment in cats." (PMID 38190419, 2024).
tumor (2 papers, 2021 to 2025). "Future research should focus on investigating the impact of TMEM138 on tumor occurrence and progression, as well as its potential for developing novel treatment methods and identifying new targets for tumor prevention, diagnosis, and treatment." (PMID 40432436, 2025). "Further exploration of TMEM138 may lead to its potential as a novel tumor-related marker for predicting patient prognosis and enabling personalized tumor treatment." (PMID 40432436, 2025). "However, the exact role of TMEM138 in tumor regulation remains unclear, necessitating further exploration of gene mutations and related signaling pathways." (PMID 40432436, 2025). "Specifically, the CDC42EP3-206 + TMEM138-211 + IRX3-202-based model achieved maximum predictive efficacy (Rs = 0.94, FDR = 1.8e-09), explaining more than 88% of the ROR variance observed across different tumor types." (PMID 34899357, 2021).
cancer (1 paper, 2021). A tumor composed of atypical neoplastic, often pleomorphic cells that invade other tissues. "CDC42EP3-206 was the most predictive of irAE risk across cancer types (Rs = 0.79, p = 5.8e-05), followed by TMEM138-211 (Rs = 0.77, p = 1.1e-04)." (PMID 34899357, 2021). "In addition, we established a trivariate model composed of CDC42EP3-206, TMEM138-211, and IRX3-202, that could better predict the risk of irAE across various cancer types, indicating a potential application as promising biomarkers for irAE." (PMID 34899357, 2021).
neurodegenerative disease (1 paper, 2025). A disorder of the central nervous system characterized by gradual and progressive loss of neural tissue and neurologic function. "Furthermore, abnormal expression of TMEM138 has been linked to a range of diseases, particularly neurodegenerative diseases and tumors." (PMID 40432436, 2025).
TMEM138 also shares sentences with these, for which no sentence is quoted: Infertility (1 paper); kidney disease (1); neurodevelopmental disorder (1); reproductive system diseases (1); retinal ciliopathy (1); retinal diseases (1); Usher syndrome (1).